CXCR4 (C-X-C motif chemokine receptor 4)
Diseases named in the same sentence as CXCR4 in open-access papers (continued):
Sharing a sentence is not in itself a finding about the gene and the disease.
tumor (continued). "Since CXCR4 has been reported to mediate tumor cell invasion and metastasis, we performed chemotaxis assays to examine the capacity of GC cells to migrate in response to SDF-1α (CXCL12), a specific ligand for CXCR4." (PMID 27007162, 2016). "Furthermore, we detected CXCR4 expression on 4T1 TDLN B cells, and 4T1 tumor cells produced its ligand CXCL12." (PMID 27528023, 2016). "In our study, we also indicated that the concentrations of CXCL12 and CXCR4 were higher in patients with resectable tumors compared to those with nonresectable EC, similarly to classical tumor markers (data not shown)." (PMID 27041792, 2016). "In particular, CXCR4 negative/CD99 positive tumor cells were present in abundance in tumors that arose from CXCR4 positive cells." (PMID 27528222, 2016). "Whereas CCR6 seems to be required for retention of LCH-cells in the various tissues, our in vitro experiments support a role for CXCR4 in the distribution of blood-borne CD1a+CD11c+CXCR4+‘LCH-cell like’ myeloid cells in analogy to both immune cells and tumor cells." (PMID 28255525, 2016). "Of interest, we found that the corresponding receptors of SDF-1α and CCL2, CXCR4 and CCR2 were up-regulated in the THP1 cells, which might amplify the chemotaxis of monocytes into the tumor sites." (PMID 27888616, 2016). "To verify this hypothesis, we analyzed expression of several markers on GFP+ tumor cells that were previously thought to characterize cancer stem cells: c-Kit, Sca-1, CD133, CD49f, and CXCR4." (PMID 26385771, 2016). "The molecular mechanism of anti-tumor activities by SDF-1 and CXCR4 inhibition could be complex in different models." (PMID 26954567, 2016). "Upon intratumoral injection of bacterial IBs formed by a potent protein ligand of CXCR4 we have observed high stability and prevalence of the material in absence of toxicity, accompanied by apoptosis of CXCR4+ cells and tumor ablation." (PMID 27775083, 2016). "The diagnostic sensitivity, negative predictive value, and accuracy of CXCR4 were the highest among all analyzed proteins and increased for combined analysis with classical tumor markers and CRP levels." (PMID 27041792, 2016). "Among them, C-X-C chemokine ligand 12 (CXCL12) and its receptor C-X-C chemokine receptor type 4 (CXCR4) seem to be involved in the development of several organs, including kidney, and they are also related to tumor growth and metastatic process in many types of cancer." (PMID 27830498, 2016). "Together show that whether diffused out of necrotic GemOE cells or released from hypoxic GemOE cells within tumor cores, Ac-HMGB1 upregulates CXCR4 on the surface of MSCs most likely through activation of RAGE." (PMID 26989079, 2016). "CXCR4-mAb treatment did not result in clear tumor growth reduction in A549 xenografts, even by the end of therapy." (PMID 26848769, 2016). "We found that the expression of CXCR4 in tumor tissues was higher than that in adjacent non-tumorous tissues." (PMID 27835898, 2016). "Previous studies that focused on phenotypic characterization of tumor-propagating cells have used various cell surface markers known to induce stem-like and mesenchymal phenotypes and/or drug resistance, such as CD117, Stro-1, CXCR4 and ABCG2, and CD133." (PMID 27634875, 2016). "The chemokine receptor 4 (CXCR4) and its only known natural ligand stromal cell derived factor-1 (SDF-1, CXCL12) have gained considerable attention in oncology, in particular its impact on tumor metastasis." (PMID 27655427, 2016). "Also, it has been demonstrated that tumor cells which express CXCR4 home bone marrow and that SDF-1 attracts MSCs from bone marrow or other sites in body to tumor tissue." (PMID 27630452, 2016).
tumor (continued). "CXCR4+ cells presented CSC characteristics, such as increased resistance to tyrosine kinase inhibitors, higher sphere-forming ability, and tumor growth-inducing potential in vivo, and expressed high levels of stem cell-associated makers NANOG, OCT3/4, and SOX2." (PMID 27293448, 2016). "The von Hippel-Lindau (VHL) is a putative tumor suppressor gene which has been proposed to exert inhibitory effects on angiogenesis and tumor cell migration, through negative regulation of HIF1 and the stromal-derived factor-1 (SDF-1) receptor, CXCR4." (PMID 27540529, 2016). "Our in vitro experiments demonstrated that IL-2 modulated expression of CD25 on B cells after activation /expansion (A/E) before adoptive transfer; enhanced CXCR4 expression on B cells; augmented CXCL12 production by 4T1 tumor cells, and increased production of perforin by B cells." (PMID 27528023, 2016). "The CXCL12/CXCR4 axis transactivates HER2 and promotes intraosseous tumor growth." (PMID 27809841, 2016). "Tumor-infiltrating MDSCs, which express CXCR4 (data not shown), accumulated in mice receiving Bay60-6583." (PMID 27590504, 2016). "Accordingly, we propose that GemOE tumor cells present within tumor cores represent metastatic precursors, and suppressing the GemOE→HMGB1/RAGE→SDF1/CXCR4 signaling circuit could be a valid target for therapies to inhibit GemOE tumors and their metastases." (PMID 26989079, 2016). "Interestingly, a recent study reported that SIVmac239-Nef decreases cell surface expression of the CXCR4 in COS-7 cells and decreases proliferation, and migration of tumor cells." (PMID 26318034, 2015). "Furthermore, these cells have increased exposure to the factors necessary for tumor relapse, including CXCL12, through its receptors CXCR4 and CXCR7, IL6 through the Jak2/Stat3 pathway, EGF, FGF and IGF, among others." (PMID 25797268, 2015). "In this study, we found that CXCR4 is not uniformly expressed in the tumor and in the course of the disease." (PMID 26083776, 2015). "In particular, we have previously shown in an orthotopic NB xenograft model, that CXCR4 mostly promoted NB primary and secondary tumor growth, without influencing organ-specific dissemination of malignant NB cells." (PMID 25955316, 2015). "In contrast, no CXCR4 was detected at protein level in EWS lung metastases with immunohistochemistry but was positive in the chemotherapy-naïve tumor biopsies where it correlated with tumor volume." (PMID 26193259, 2015). "CD133, CD44, CD24, CDCP1, CXCR4, and CD26 have been identified as colon CSC surface antigens, but it is not well defined which are the best markers to identify a tumor stem cell due to the variability found among individuals with the same tumor type." (PMID 25685060, 2015). "In addition, our findings show that the activated platelet culture supernatant upregulated the expression of CXCR4 on the surface of SW620 cells, suggesting platelets actively induce the migration of tumor cells into blood vessels." (PMID 25846512, 2015). "Taken together, our data suggest that the CXCR4 is involved in the attachment to the peritoneum but not in the tumor nodule formation." (PMID 26110809, 2015). "Although shRNA-based knockdown of CXCR4 attenuated SDF-1-mediated migration but did not affect to the tumor nodule-formation ability (not shown), CXCR4- population were decreased tumorigenesis and a colony formation ability." (PMID 26110809, 2015). "These novel oncogenic mechanisms, in addition to the dissemination of CXCR4+ tumor cells to distant lymphatic tissues with high CXCL12 concentrations, may synergistically account for the CXCR4-mediated disease progression." (PMID 25704881, 2015). "Additionally, CXCR4 seems to be involved in tumor-stroma interactions, thus leading to protection of the SCLC tumor cells from chemotherapy-induced apoptosis." (PMID 25671300, 2015).
tumor (continued). "Indeed, individual inhibitors of CXCR4, CXCR7 (CCX2066, ChemoCentryx), and CXCR3 (AMG487) showed partial effectiveness in reducing tumour growth and metastasis and they are still in preclinical studies." (PMID 26062132, 2015). "On the other hand, the expression of FGF2, as well as CXCR4, CD45 and COL1A1, in the isolated fibrocyte-like cells was similar between the tumours, suggesting that the increase of FGF2 in bevacizumab-treated tumours was due to the increase in the number of these cells." (PMID 26635184, 2015). "As investigated in vivo, using an orthotopic model of tumor cell implantation of chemokine receptor-overexpressing NB cells (IGR-NB8), the CXCR4/CXCR7/CXCL12 axis was shown to regulate NB primary and secondary growth, although without any apparent influence on organ selective metastasis." (PMID 25955316, 2015). "In contrast, the other two cell lines (HSC-44 and HSC-58) showed no or quite low CXCR4 expression, a single or few peritoneal tumor nodule and did not accumulate ascites." (PMID 26110809, 2015). "As in other tumor entities, CXCR4 overexpression significantly correlates with negative patient outcome." (PMID 25671300, 2015). "Phosphoinositide 3-kinase (PI3K) and mitogen-activated protein kinase (MAPK) pathways have been found to critically affect tumor cell survival and migration, and are important downstream pathways involved in CXCL12/CXCR4 interactions, as summarized in our previous study." (PMID 25997540, 2015). "The expression of CXCR4 in lysates of tumor and parent cells was confirmed by western blot (data not shown)." (PMID 26318034, 2015). "The recruitment of these MDSC subtypes to tumor sites is mediated by chemokines highly expressed by tumor-associated neutrophils, including CXCR2 and CXCR4, and chemokines over-expressed by tumor infiltrating macrophages, including CCR2, CCR5, CXCR4 and CX3CR1." (PMID 26462153, 2015). "Given the potential roles of CXCR4 in tumorigenesis, MDA-MB468 cells were then used to study whether Nef-M1 peptide inhibits tumor angiogenesis and EMT through the CXCR4 receptor." (PMID 26318034, 2015). "Lentiviral shRNA-induced knockdown of CXCR4 in 60As6 attenuated SDF-1-mediated invasion but not affected the tumor nodule formation in the peritoneal cavity of mice (not shown)." (PMID 26110809, 2015). "The expression of CXCR4 is low or absent in many healthy tissues, but it is demonstrated that CXCR4 is highly expressed in various different tumor types and has been considered the most widely expressed chemokine receptor in cancer." (PMID 25669980, 2015). "CXCR4 expression, which was increased after CSC-EV stimulation, is known to be involved in MSC migration through a SDF-1 concentration gradient secreted by tumor cells." (PMID 25797265, 2015). "Finally, IL-24 when combined with CXCR4 inhibitors (AMD3100, SJA5) or with CXCR4 siRNA demonstrated enhanced inhibitory activity on tumor cell migration." (PMID 25775124, 2015). "Recently, a number of studies have indicated that activation of TLR4 by LPS might elevate CXCR4 and/or CXCR7 expression in tumor cells, enhancing the response to SDF-1 to promote invasion and cell dissemination." (PMID 26288180, 2015). "Interestingly, the number of GFP-positive cells was significantly increased in the bevacizumab-resistant tumours, and the collagen type I+/CXCR4+ cells were also GFP-positive, suggesting that the origin of the collagen type I+/CXCR4+ cells was the bone marrow." (PMID 26635184, 2015). "CXCR4 selectively binds to CXC chemokine stromal cell-derived factor 1α (SDF-1α or CXCL12), and CXCL12/CXCR4 signaling is regarded as a candidate factor involved in the tumor-stromal interactions." (PMID 25605248, 2015).
tumor (continued). "Interestingly, MIF, which is secreted in response to hypoxia by different tumor cells, was reported to induce CD11b+GR1+ myeloid cell migration via CD74/CXCR4 and CD74/CXCR2 complexes, as well as through p38 and PI3K activation." (PMID 26347749, 2015). "MMP-2, MMP-9, LOX, CXCR4, FN and p-FAK are involved in remodeling the tumor metastatic microenvironment, and whether miR-33b can regulate the metastatic microenvironment deserves further investigation." (PMID 25919570, 2015). "Several CXCR4 antagonists have already been synthesized (e.g., AMD3100 (plerixafor), AMD3465, TF 14016, BMS-936564), which display a high anti-proliferative capacity both in vitro and in different animal tumor models." (PMID 26259237, 2015). "Thus, preclinical data showed that inhibition of CXCR4 by neutralizing antibodies, siRNAs, and antagonists such as AMD3100 (Plerixafor, Mozobil) and MSX-122 (Metastatix, phase I trial) can inhibit tumor growth and reduce metastasis." (PMID 26062132, 2015). "Thus, SDF-1-CXCR4 axis-mediated homing of tumor cells to the BM is commonly observed in various hematopoietic malignancies and carcinomas including HNSCC, whereas inhibition of CXCR4 blocks this homing." (PMID 25504440, 2015). "As a critical mediator of tumor–stroma interactions, CXCL12/CXCR4 axis plays an important role in the bidirectional tumor-stromal interaction, and therefore may be a promising prognostic marker and therapeutic target in PDAC." (PMID 25679210, 2015). "In this study, our results demonstrated that HBx stimulates the neoplastic transformation of normal cells and tumor induction by AFP triggering of the PI3K/mTOR signal to promote expression of Src, Ras, and CXCR4, which are known to promote the progression, invasion, and metastasis of cancer cells." (PMID 25682869, 2015). "Previous studies have indicated that the activation of Toll-like receptors (TLRs) by lipopolysaccharide (LPS) might elevate CXCR4 and/or CXCR7 expression in tumor cells, enhancing the response to SDF-1 to promote invasion and cell dissemination." (PMID 26288180, 2015). "CXCL12 secretion by stromal cells attracts cancer cells, acting through its cognate receptor CXCR4, which is expressed by both haematopoietic and non-haematopoietic tumour cells." (PMID 25598217, 2015). "MSCs may be recruited into the tumor through FPR2, CCR2, CXCR1, CXCR2, CXCR4, CXCR6, and CX3CR1 depending on the types and locations." (PMID 25110692, 2014). "Systemic administration of d-Arg3FC131, a CXCR4 antagonist, inhibits the growth of GH3 somatotrope tumor cell xenografts in immunodeficient nude mice by inducing apoptosis and suppressing the proliferation of tumor cells." (PMID 24647809, 2014). "Transcripts of other genes such as chemokine ligand-2 (Ccl2) and chemokine receptor-4 (Cxcr4) were not affected in bone marrow by tumor ablation." (PMID 24270800, 2014). "Furthermore, we found that 4EGI-1 selectively inhibits translation of mRNAs encoding proteins that are enhanced in CSC maintenance, proliferation and metastasis, such as NANOG, OCT4, c-MYC, cyclin D1, CXCR4, VEGF and c-MYB, in breast CSC tumor cells." (PMID 25115391, 2014). "Interestingly, inhibitors of CXCR-4, CXCR-7, and SDF-1 have all demonstrated delayed (or blocked) tumor recurrence post-RT in animal tumor growth-delay experiments." (PMID 24478982, 2014). "A CCK-8 assay was performed to determine the proliferation of tumor cells in vitro and the result revealed that compared with the negative and blank control groups, the proliferation of CXCR4-shRNA was significantly inhibited (P<0.05)." (PMID 25202367, 2014). "Conceivably, the combination of CXCR4 and CXCR7 antagonists could represent powerful tool to reduce tumor cell invasion and metastasis." (PMID 24904289, 2014).
tumor (continued). "Furthermore, in a recent phase I study of another CXCR4 inhibitor LY2510924 for advanced cancer, the circulating tumor cell (CTC) counts were included as one of the study endpoints in addition to safety, pharmacokinetics, efficacy, and pharmacodynamics." (PMID 25471741, 2014). "Tumor-bearing mice were treated at 4-day intervals by tail-vein bolus injections of the monoclonal anti-CXCR4 antibody (mAb 12G5), known to block the binding of CXCL12 to CXCR4 and to inhibit CXCL12-evoked chemotaxis in vitro." (PMID 24390633, 2014). "Here, we hypothesized that in GBM, CXCR4 antagonism works by blocking the TIC supportive effects of the PVN, and that in combination with VEGF antagonism, would exert superior anti-tumor effect by inhibiting PVN formation and function." (PMID 25238146, 2014). "The homeostatic chemokine CXCL12 was expressed outside malignant nodules whereas its receptor CXCR4 was identified within tumour but not on CD8+ cells." (PMID 24961933, 2014). "CXCR4 expression distribution was not significantly different in age, sex, differentiation degree, and tumor size groups." (PMID 25471741, 2014). "In particular, knocking down CXCR4 using RNAi or inhibiting CXCR4 function by AMD3100 in CSCs, impairs proliferation in vivo, effectively reducing tumor growth in two different xenograft models; similarly shRNA CXCL12 knock-down in CSCs inhibited tumor growth in vivo." (PMID 24904289, 2014). "In the group of patients exhibiting other organ metastases, CXCR4 over-expression in tumor tissue was also higher compared with the patients without metastases." (PMID 24932250, 2014). "CXCR4 has been shown to be one of the key drivers in tumor progression as we have seen that knockdown of CXCR4 in a HeyA8 xenograft model showed tumor growth inhibition (data not shown)." (PMID 25514788, 2014). "Recent studies have examined the cell-free mRNA expression of several genes, including TS, β-catenin, hTERT, CK19, MUC1, CXCR4, Bmi-1, Her-2 and DKK1, these studies have focused on the use of cell-free mRNA for early diagnosis, tumor staging and disease monitoring." (PMID 25496700, 2014). "CXCR4 also sustains non-pharmacological resistance of tumor cells, through its effects on the stromal microenvironment that supplies growth- and drug-resistance signals to tumor cells." (PMID 24904289, 2014). "Interaction of CXCR4 with its ligand, stromal derived factor (SDF-1α, CXCL12) directs the movement of cells in hematopoietic stem cell homing, leukocyte trafficking and tumour metastasis." (PMID 24885150, 2014). "In previous studies, CXCR4 was identified in the tumor nests of HNSCC, but not in the surrounding stroma of the CSC niche." (PMID 24348826, 2014). "In addition, CXCR4 is expressed on various cancer cell types, and the CXCL12–CXCR4 axis is involved in tumor progression, angiogenesis, metastasis, and survival." (PMID 24477286, 2014). "Tumor induced changes such as hypoxia is involved in the up-regulation of HIF1-α followed by induction of Stromal Cell Derived Factor-1 Alpha (SDF1α) and secretion of various pro-angiogenic factors and recruitment of CXCR4+BMDCs." (PMID 26925346, 2014). "Furthermore, CXCL12 stimulates VEGF secretion in CXCR4-expressing, CD133+ CSCs from surgical specimens of human GBM and cell lines, promoting tumor angiogenesis via PI3K/AKT signaling." (PMID 24904289, 2014). "CXCR-4 has been proven to be expressed in pancreatic intraepithelial neoplasia (PanIN), PDAC, and especially the metastatic site playing a crucial role in lymphangiogenesis and regulation of tumor cell proliferation, metastasis, and chemoresistance." (PMID 24587996, 2014). "Others have shown that hypoxia increases CXCR4 expression through HIF-1α activation and that HIF-1α enhances the expression and function of CXCR4 in normal cells monocytes, macrophages and endothelial cells and in tumor cells." (PMID 24629239, 2014).